IL6 (interleukin 6)
Diseases named in the same sentence as IL6 in open-access papers (continued):
Sharing a sentence is not in itself a finding about the gene and the disease.
breast cancer (continued). "IL-6 signaling not only exerts its effects on breast cancer cells, but can also play a role in the surrounding tumor microenvironment, indirectly impacting cancer growth and progression." (PMID 26840088, 2016). "Among the IL-6 targeting agents, raloxifene and bazedoxifene, have been studied as anti-breast cancer agents based on a mechanism involving antagonizing estrogen action." (PMID 26840088, 2016). "There existed a reduction in proliferation following IL-6 knockdown on basal-like breast cancer cells including MDA-MB-231 and Hs578T cells." (PMID 27231908, 2016). "Drug resistance is a critical problem in breast cancer therapy, and autocrine production of IL-6 by breast tumor cells promotes resistance to multi-drug chemotherapy." (PMID 26840088, 2016). "The pleiotropic cytokine IL-6 accelerates the progression of breast cancer in a variety of preclinical models through the activation of the STAT3 (signal transducer and activator of transcription 3) signaling pathway." (PMID 27602583, 2016). "Further studies are warranted to assess the potential of utilization of HER2 therapies in combination with IL-6 therapies to overcome drug resistance in HER2-positive breast cancers." (PMID 26840088, 2016). "IL-1β treatment induced IL-6 production in TG2-overexpressing breast cancer cells and resulted in an aggressive phenotype that showed increased invasion, EMT phenotypes, and cancer stem-cell-like properties." (PMID 27609180, 2016). "STAT3 phosphorylation in breast epithelial cells can be stimulated by paracrine signaling through IL-6 from both breast cancer cells and fibroblasts." (PMID 26840088, 2016). "Curcumin, an IL-6 inhibitor, can reduce the production of IL-6 in breast cancer to reduce the number of MDSCs." (PMID 27542274, 2016). "Expressions of IL-6 have also been observed to be higher in the primary tumour tissues than the adjacent normal tissues in prostate cancer, breast cancer, and esophageal squamous cell carcinoma as well as gastric cancer." (PMID 27034885, 2016). "In breast cancer patients, the increase in serum IL-6 correlates with poor disease outcome and prognosis." (PMID 27602583, 2016). "We have recently shown that the aggressive breast cancer MDA-MB-231 cells as well as the interleukin-6 recombinant protein can activate breast stromal fibroblasts in a STAT3-dependent manner." (PMID 27248826, 2016). "IL-1β induced IL-6 production in breast cancer cells in a TG2-dependent manner, and other cytokines and growth factors including TGF-β, TNF-α, and EGF potentiated the effect of IL-1β on IL-6 expression." (PMID 27609180, 2016). "We have shown here that breast cancer cells and IL-6 persistently activate breast stromal fibroblasts through the stimulation of the positive IL-6/STAT3/NF-κB feedback loop." (PMID 27248826, 2016). "Upregulation of IL-6 has been reported in breast cancer and increased serum IL-6 levels are observed in advanced breast tumor stages." (PMID 27153074, 2016). "In breast cancer, the cytokines concerned with the differentiation of MDSCs from bone marrow progenitors include G-CSF, M-CSF, GM-CSF, IL-6, IL-1β, macrophage migration inhibitory factor (MIF), TGF-β1." (PMID 27542274, 2016). "Similar findings were reported by other studies in which TCT isomers reduced IL-6 and gene protein expression in LPS-stimulated macrophages and murine mammary cancer cells with δ-TCT being the most potent, followed by γ-TCT." (PMID 27396399, 2016). "IL-6 and its downstream signal network (IL-6/IL-6R/gp130) are reported to play important roles in breast cancer." (PMID 27231908, 2016). "Accordingly, blockade of IL-6 signaling, through the inactivation of its signaling receptor (gp130), reduces the aggressiveness of breast cancer cells in a variety of assays." (PMID 27602583, 2016). "Previous studies have shown that CAFs production of CXCL1, CXCL2, PTGS2/COX-2, and IL-6 in breast cancer can modulate the functions of immune cells in TME." (PMID 26884644, 2016).
breast cancer (continued). "IL-6 secreted from senescent mesenchymal stem cells can increase the proliferation and migration of breast cancer cells by induction of STAT3 phosphorylation." (PMID 26840088, 2016). "Since STAT3 can be activated by a variety of cytokines, including IL-11, CNTF, LIF and G-CSF, in breast cancer, it is crucial to identify those tumors that depend on IL-6." (PMID 27602583, 2016). "This study evaluated the genetic associations of IL6-174 (rs1800795 G>C) and TNF-308 (rs1800629 G>A) with CACI and cytokine fluctuations within an Asian early-stage breast cancer population." (PMID 27701469, 2016). "6a is a pyrrolidinesulphonylaryl synthetic molecule that suppresses IL-6 signaling in the MDA-MB-231 breast cancer cell line via selective inhibition of STAT3 phosphorylation and transcription." (PMID 26840088, 2016). "This study evaluates the efficacy of anti-IL-6 therapies using breast cancer patient derived xenografts (PDXs)." (PMID 27602583, 2016). "IL-1β induced IL-6 production from TG2 overexpressing MCF7 breast cancer cells in an NF-kB-, PI3K-, and JNK-dependent manner." (PMID 27609180, 2016). "Within the inflammatory tumor microenvironment, IL-1β increases luminal-type breast cancer cell aggressiveness by stimulating IL-6 production through a TG2-dependent mechanism." (PMID 27609180, 2016). "In this study, we found that A1CF (-8aa) can promote proliferation of breast cancer cells mostly likely by stabilizing the mRNA of IL-6." (PMID 27231908, 2016). "A knockdown (KD) of TG2 in MDA-MB-231 breast cancer cells reduced IL-6 expression, and a knockdown of both TG2 and IL-6 inhibited tumor growth and metastasis." (PMID 27609180, 2016). "IL-6 produced by tissue-specific fibroblasts promotes the growth and invasion of breast cancer cells through STAT3-dependent up-regulation of Notch-3, Jagged-1, and carbonic anhydrase IX." (PMID 26840088, 2016). "Emerging evidence suggests that high levels of IL-6 are correlated with poor prognosis in breast cancer patients." (PMID 26840088, 2016). "Trastuzumab resistance in HER2-overexpressing breast cancer cells is shown to be mediated by the IL-6 inflammatory loop, leading to expansion of the breast cancer stem cell population." (PMID 26840088, 2016). "An elevated level of IL-6 mediated Jagged1/Notch signaling was also proposed to promote breast cancer bone metastasis." (PMID 27462787, 2016). "Since IL-6 plays a critical role in BTIC expansion in HER2-positive breast cancer cells, we next examined the stemness property of these resistant cells using spheroid formation and aldehyde dehydrogenase (ALDH) activity assays." (PMID 27694691, 2016). "IL-6/STAT3 signaling has been shown to be essential for the paracrine activity of senescent breast cancer cells." (PMID 27489164, 2016). "Increased invasion of MCF7_TG2 breast cancer cells by IL-1β was attenuated by blocking IL-6 through anti-IL-6 antibody treatment." (PMID 27609180, 2016). "In the current report, inhibition of IL-6 signaling with tocilizumab yielded significant growth retardation, in orthotopic breast cancer, implicating IL-6 as a key mediator of tumor progression." (PMID 27329584, 2016). "The results show that IL-1β induced expression of IL-6 in breast cancer cells, and that TG2 overexpressing cells expressed over twenty times more than control cells after IL-1β treatment." (PMID 27609180, 2016). "In patients with advanced breast cancer, docetaxel therapy was associated with an increase in serum IFN-γ, IL-2, and IL-6 levels and enhancement of circulating NK cell activity." (PMID 27777963, 2016). "In this nested case-control study, we analyzed several biomarkers of inflammation that is ox-LDL, IL-1β, IL-6, TNF-α, WBC, neutrophils, and lymphocytes, and found significant associations between ox-LDL, IL-1β, and TNF-α and post-menopausal breast cancer." (PMID 27391324, 2016).
breast cancer (continued). "The active IL-6/STAT3/NF-κB positive feedback loop in CAFs from breast cancer patients shows an important role of this epigenetic switch in sustaining the activated phenotype of CAFs in the absence of cancer cells." (PMID 27248826, 2016). "MDSCs act on T cells and NK cells to suppress the body's immunity, and via IL-6 trans-signaling, promote breast cancer directly." (PMID 27542274, 2016). "In breast cancer xenografts, IL-6 activates STAT3 by binding to its receptor (gp130) and directly stimulates breast CSC self-renewal." (PMID 26980947, 2016). "IL-6 has also been reported to stimulate the proliferation and migration of breast cancer cells in vitro as well as tumor progression, but its potential connection with radiotherapy was less studied." (PMID 27282478, 2016). "The importance of the IL-6 and other cytokines as a prediction factor of shorter progression-free survival was shown previously in patients with ovarian cancer and breast cancer." (PMID 26759169, 2016). "Next, we have examined the expression level of two other cytokines produced by breast cancers, namely IL-6 and IL-8, which have been shown to increase growth and metastatic potential of breast cancer cells." (PMID 26888313, 2016). "IL-6 regulates normal stem cell self-renewal in the breast and induces malignancy in stem cells from human breast carcinoma." (PMID 27602583, 2016). "Several recent studies indicate that IL-6 is a novel Notch target in breast cancer cells and enhanced Notch signaling upregulates the IL-6 expression, leading to activation of autocrine and paracrine Jak/STAT signaling." (PMID 25669984, 2015). "Autocrine loops are highly relevant in cancer progression and, in particular, the importance of IL-6 autocrine signaling in breast cancers is well known." (PMID 26512918, 2015). "Paracrine roles of the IL6 protein are still less understood, warranting further studies, particularly in the luminal subtype of breast cancer and in other stromal cells in basal breast cancer." (PMID 26173622, 2015). "IL6 mRNA expression is higher in basal breast cancer when compared to other subtypes of breast cancer." (PMID 26173622, 2015). "We performed 123I-mIBG scintigraphy, conventional and strain echocardiography and biomarker (NT-proBNP, TNF-α, galectin-3, IL-6, troponin I, ST-2 and sFlt-1) assessment in 59 breast cancer survivors 1 year after anthracycline treatment." (PMID 26400150, 2015). "The molecular profile analysis of breast cancer stem tumorigenic cells revealed an upregulation of IL-6 and of Notch-3, a stem cell regulatory gene." (PMID 25881039, 2015). "Surprisingly, we observed that GP130, a functional receptor gene for IL6 signal transduction, has lower mRNA expression in basal breast cancer, compared to luminal breast cancer." (PMID 26173622, 2015). "A few studies have suggested that the activation of an IL6 inflammatory loop through STAT3 mediates trastuzumab resistance in HER2-positive breast cancer by expanding the cancer stem cell population and by promoting epithelial-mesenchymal transition." (PMID 26234940, 2015). "The role of IL6 signaling has been widely investigated in the development of various types of cancer, including liver, lung and breast cancer." (PMID 25824986, 2015). "In particular, we show that IL-6 upregulates its own mRNA, thus perpetuating the effects of transient IL-6 exposure of breast cancer cells." (PMID 25881039, 2015). "Overexpression of YB-1 in breast cancer cell lines induced IL-6 production while stimulation with IL-6 increased YB-1 expression and YB-1 phosphorylation." (PMID 26512918, 2015). "It has also been reported that IL-6 induces malignant phenotypes in Notch-expressing stem/progenitor cells from human breast cancer." (PMID 25669984, 2015). "For example, breast cancer patients often present with increased levels of circulating TNFα and IL-6, suggesting a heightened inflammatory state that correlates with hastened metastatic progression and death." (PMID 26177198, 2015).
breast cancer (continued). "Both IL-6 and IL-8 can be highly expressed in TN breast cancers and this has partly been attributed to constitutively active NFκB." (PMID 26392082, 2015). "We recently reported that enhanced production of MMP-8 by breast cancer cells induced the expression of the proinflammatory mediators interleukin-6 (IL-6) and IL-8." (PMID 25848906, 2015). "Our results are in concordance with data for breast cancer and glioblastoma showing IL6-dependent promotion of cell invasion into the basal membrane and CAM, respectively." (PMID 26215971, 2015). "Meanwhile, adipocytes co-cultured with breast cancer cells exhibited increased expression of proteases such as matrix metalloproteinase-11 and pro-inflammatory cytokines, such as IL-6." (PMID 25823469, 2015). "Our findings will be directly examined in a planned clinical trial of combined HER2 and IL-6 targeted therapy in HER2-positive breast cancer." (PMID 26397099, 2015). "The breast cancer cells (BT20) secreted high levels of IL6 when co-cultured with MRC5 cells and primary TAFs whereas, the monocultures and co-cultures of lung cancer cells (H596) secreted only moderate levels of IL6." (PMID 26053043, 2015). "Tumor suppressive role of miR-146b in breast cancer cells have been proposed where overexpression of miR-146b suppressed NF-κB dependent expression of IL-6 and subsequent invasiveness and mesenchymal phenotype of breast cancer." (PMID 26569605, 2015). "For example, N-3-oxo-dodecanoyl-homoserine lactone, a quorum sensing molecule secreted by Ps.aeruginosa, induces apoptosis in several breast cancer cell lines and enhances the production of interleukins (IL-6, IL-8) in bronchial epithelial cells." (PMID 25995981, 2015). "In the present work, we explored the relationship between YB-1 and IL-6 signaling in the acquisition of EMT characteristics by breast cancer cells." (PMID 26512918, 2015). "We explored the possible involvement of NF-κB in inhibition of HRD1 expression in breast cancer cells by treating MCF-7 cells with IL-6." (PMID 26536657, 2015). "Predictions from our simulations of niche target inhibitors match experimental data demonstrating the efficacy of combined HER2 and IL-6 blockade in pre-clinical models of HER2-positive breast cancer." (PMID 26397099, 2015). "This is further established in mouse models of breast cancer in which ablation of TNFα or IL-6 results in reduced metastasis." (PMID 26177198, 2015). "The additional predictive value of IL-6, supplementary to that of clinical frailty assessment, for outcome and treatment toxicity in (breast) cancer patients should be explored in the future." (PMID 25989735, 2015). "MRTFA was enriched in BLBC and was positively correlated with MaSC/progenitor cell signature and IL6 expression, whereas MRTFB was enriched in luminal-type breast cancer and was negatively correlated with MaSC/progenitor cell signature and IL6 expression." (PMID 26671411, 2015). "Breast cancer tissues express high levels of IL-6 as compared with matched normal tissues and these levels increase with tumor grade." (PMID 26338965, 2015). "Chromatin immunoprecipitation analysis revealed that breast cancer cells treated with leptin and IL-6 (used as a positive control) showed increased recruitment of Stat3 at the miR-34a promoter while HNK treated cells showed decreased Stat3 recruitment." (PMID 26036628, 2015). "Increased levels of pro-inflammatory cytokines, including IL-6, in tumors and serum of breast cancer patients correlate with poor prognosis." (PMID 26268945, 2015). "Shk also restricted the increase in CSC load in MCF7 cells on IL6 treatment, indicating that it is able to restrict the native and induced stemness in breast cancer." (PMID 25973915, 2015). "The idea that YB-1 is a transcription factor that activates IL-6 promoter activity is in agreement with a ChIP sequencing study in trastuzumab-resistant breast cancer cells that identified IL-6 and IL-6R as YB-1 transcriptional targets." (PMID 26512918, 2015).
breast cancer (continued). "The survival of the breast cancer cells (BT20) in co-culture with MRC5 cells was significantly reduced (approximately 50%) upon treatment with by mAb IL6." (PMID 26053043, 2015). "We have also shown that the increase in the expression/secretion of IL-6 in p16-defective cells is responsible for the paracrine pro-invasive/migratory effects of these cells on breast cancer cells." (PMID 26338965, 2015). "The effects of IL-6 signaling inhibitors on breast cancer cell morphology and proliferation have been evaluated in monotypic cultures." (PMID 26268945, 2015). "The inductions of total or secreted IL-6 level by lapatinib in a time-dependent manner were further found in primary human breast cancer cells from two TNBC patients (respectively)." (PMID 26513016, 2015). "In accordance with the critical roles of chronic inflammation and immune cells in causing changes in microenvironment during tumorigenesis, IL-6 signaling is required for CSC maintenance in glioma, lung, colon, and breast cancer." (PMID 26593949, 2015). "Among these genes, AP3B1, ONECUT2 and IL-6 were already confirmed to be direct targets of miR-9 in breast cancer, insulin-producing cells, and cervical adenocarcinoma, respectively, which demonstrated the reliability of our screening strategy." (PMID 26547929, 2015). "These modeling results will be directly examined in a planned clinical trial of HER2 and IL-6 targeted therapy for breast cancer patients." (PMID 26397099, 2015). "A previous study demonstrates that development of trastuzumab resistant in breast cancer cells is mediated by activation of an IL-6 inflammatory feedback loop." (PMID 25669984, 2015). "Another study reported that fibroblasts isolated from breast cancer tissue enhances cancer cell invasiveness through an interleukin-6 (IL-6)-dependent signaling mechanism." (PMID 26517671, 2015). "Overall, these data suggest that there is a potential link between IL6-pSTAT3-PTEN loss, stroma reactivation, and primary trastuzumab resistance in HER2-positive primary breast cancers." (PMID 26234940, 2015). "Secreted TGF-β1 and IL-6 especially but also IL-8 and MMPs have been long recognized to release cell-to-cell contacts of breast cancer cells and initiate metastasizing behavior." (PMID 26000019, 2015). "There is a direct correlation between serum IL-6 levels and poor prognosis in breast cancer patients." (PMID 26268945, 2015). "It has been reported that HOXB13 protein mediates tamoxifen resistance and invasiveness in luminal breast cancer by suppressing estrogen receptor (ER) and inducing IL6 protein expression." (PMID 26173622, 2015). "We have recently shown that IL-6 is involved in breast cancer cells–dependent activation of breast stromal fibroblasts." (PMID 26338965, 2015). "Here, we show that Notch-3-dependent ERK activation in breast cancer via IL-6 targets the activation of Jagged-1, which belongs to a family of Notch ligands and CA-IX, a hypoxia survival gene." (PMID 25881039, 2015). "Accordingly, an IL-6/STAT3 pathway was preferentially active in CD44+/CD24- breast cancer stem cells and PTEN was shown to negatively regulate TIC manteinance through STAT3-dependent signalling." (PMID 26486080, 2015). "Markers of inflammation cytokines, including IL-6 and IL-8, are expressed at high levels in the tumor microenvironment as well as during and after radiation and chemotherapy for breast cancer." (PMID 25793000, 2015). "Breast cancer cell line MDA-MB-231 upon exposure to DOX shows an increase in IL-6 levels more than the already elevated IL-6 levels." (PMID 26767086, 2015). "Previous research also indicated that increased resistance to apoptosis in human breast cancer was induced by high expression of IL-6 and IL-6R." (PMID 26313265, 2015). "In this report, we demonstrate that SF is capable of disrupting NF-κB p65 translocation, transcriptional activity, and inhibiting endogenous target IL-6 at mRNA and secreted protein level across breast cancer cell lines." (PMID 26522776, 2015).